SMN1 (survival of motor neuron 1, telomeric)
Diseases named in the same sentence as SMN1 in open-access papers (continued):
Sharing a sentence is not in itself a finding about the gene and the disease.
neurodegenerative disease (19 papers, 2008 to 2025). A disorder of the central nervous system characterized by gradual and progressive loss of neural tissue and neurologic function. "SMA is a rare, progressive neurodegenerative disease caused by homozygous deletion or mutation of the SMN1 gene on chromosome 5q13." (PMID 38468256, 2024). "SMA is a severe neurodegenerative disease, the most common in infancy due to genetic causes: the autosomal recessive gene (SMN1) is carried by one person over 35/50." (PMID 30233310, 2018). "SMA is a rare example of a monogenetic neurodegenerative disease: the causative factor of SMA is the loss of SMN, a protein encoded by the SMN1 gene." (PMID 35628657, 2022). "A point mutation (5% of cases) or a deletion (95%) of the SMN1 gene, which encodes the SMN protein, results in the inherited neurodegenerative disease spinal muscular atrophy." (PMID 24923560, 2014). "Many important questions remain regarding the pathology of the disease, including why the ubiquitously expressed SMN1 protein primarily impacts motor neurons, which other organs are potentially affected by SMN1 deficiencies, and whether SMA is a developmental or degenerative disease (or both)." (PMID 32218991, 2020). "SERBP1-associated proteins contain several factors involved in neurological disorders and neurodegenerative diseases, including FMR1, SMN1, and PABPN1." (PMID 39937575, 2025). "This review will discuss how SMN1 and SMN2 CNVs are detected and why accurate measurement of SMN1 and SMN2 copy numbers is relevant for SMA and other neurodegenerative diseases." (PMID 27014701, 2016).
tumor (19 papers, 2014 to 2025). "FADD and KIAA family-related genes were also implicated in tumor progression, while SMN1 showed connections to immune function and poor prognosis in related tumors." (PMID 37760507, 2023). "ECM-myCAFs are typically located near tumor tissue and exhibit a matrix secretory phenotype with high survival rates of motor neuron 1 (SMN1, SMA) expression." (PMID 38693304, 2024). "In tumor tissues, the staining intensity of the target genes was strong (BID, HPRT1, SMN1), high (PGAM5), or medium (FADD, KIAA1191)." (PMID 37760507, 2023).
cancer (6 papers, 2017 to 2024). A tumor composed of atypical neoplastic, often pleomorphic cells that invade other tissues. "In addition, mechanistic studies on a cellular model of cancer found that nuclear factor (erythroid-derived 2)-like 2 (NRF2) is able to bind two antioxidant-response sites in the SMN1 promoter and that NRF2 transcriptionally controls the production of SMN mRNA." (PMID 39125934, 2024).
neurological disorders (5 papers, 2018 to 2025). "The approval of AAV9.SMN1, with intravenous delivery of AAV9 for SMN1 gene therapy to lower motor neurons, marked significant advancement in gene therapy for treating neurological disorders." (PMID 39069631, 2024).
infection (1 paper, 2023). The state of being infected such as from the introduction of a foreign agent such as serum, vaccine, antigenic substance or organism. "The levels of SMN-1, Sm, and fibrillarin proteins remained constant throughout infection." (PMID 37795984, 2023).
SMN1 also shares sentences with these, for which no sentence is quoted: liver fibrosis (6 papers); Duchenne muscular dystrophy (5); breast carcinoma (4); Huntington disease (4); phenylketonuria (4); Rett syndrome (4); inherited retinal dystrophy (3); renal fibrosis (3); autosomal recessive disease (2); deafness (2); Down syndrome (2); Dubowitz disease (2); fragile X mental retardation syndrome (2); glomerulonephritis (2); glomus tumor (2); hemophilia B (2); lymph node metastasis (2); Menkes disease (2); muscular disorder (2); muscular dystrophies (2); thalassaemia (2); Wilson disease (2); acute liver failure (1); adenoid cystic carcinoma (1); Alpha-thalassemia (1); Alzheimer disease (1); Angelman syndrome (1); aortic valve disease (1); Areflexia (1); atherosclerosis (1).
A further 97 diseases each share a sentence with SMN1 in 1 paper.